CHRM3 (cholinergic receptor muscarinic 3)
Description:
The muscarinic acetylcholine receptor mediates various cellular responses, including inhibition of adenylate cyclase, breakdown of phosphoinositides and modulation of potassium channels through the action of G proteins. Primary transducing effect is Pi turnover.
Synonyms: m3AChR; EGBRS; HM3; PBS
Tractability: Small molecule: an approved drug acts on it; a structure with a bound ligand is known; a high-quality ligand is known; it belongs to a druggable protein family. Antibody: UniProt places it where antibodies can reach, with high confidence; its Gene Ontology location is reachable by antibodies, with high confidence; UniProt predicts a signal peptide or a membrane-spanning region; the Human Protein Atlas places it where antibodies can reach. PROTAC: its protein half-life has been measured; a small molecule that binds it is known.
Target class: Small molecule receptor (family A GPCR); Acetylcholine receptor; Monoamine receptor; Family A G protein-coupled receptor; Membrane receptor
Chemical probes: BATEFENTEROL, CHEMBL212141
Safety:
Unwanted effects reported when the protein is acted on. In parentheses: how it was acted on, where the effect was seen, and who reports it.
blurred vision (Bowes et al. (2012): inhibition, pulmonary, gastrointestinal; Lynch et al. (2017): inhibition, acute dosing and activation, acute dosing, nervous system, respiratory, liver, cardiovascular, gastrointestinal)
bronchoconstriction (Bowes et al. (2012): activation, pulmonary, gastrointestinal; Lynch et al. (2017): activation, acute dosing, nervous system, respiratory, liver, cardiovascular, gastrointestinal)
constipation (Lynch et al. (2017): inhibition, acute dosing, nervous system, respiratory, liver, cardiovascular, gastrointestinal; Bowes et al. (2012): inhibition, pulmonary, gastrointestinal)
dry mouth (Bowes et al. (2012): inhibition, pulmonary, gastrointestinal; Lynch et al. (2017): inhibition, acute dosing, nervous system, respiratory, liver, cardiovascular, gastrointestinal)
increased salivation (Bowes et al. (2012): activation, pulmonary, gastrointestinal; Lynch et al. (2017): activation, acute dosing, nervous system, respiratory, liver, cardiovascular, gastrointestinal)
abdominal cramps (activation, acute dosing; nervous system, respiratory, liver, cardiovascular, gastrointestinal; source: Lynch et al. (2017))
acidosis (activation, acute dosing; nervous system, respiratory, liver, cardiovascular, gastrointestinal; source: Lynch et al. (2017))
bronchorrhea (activation, acute dosing; nervous system, respiratory, liver, cardiovascular, gastrointestinal; source: Lynch et al. (2017))
bronchospasm (activation, acute dosing; nervous system, respiratory, liver, cardiovascular, gastrointestinal; source: Lynch et al. (2017))
centrilobular liver congestion (activation, acute dosing; nervous system, respiratory, liver, cardiovascular, gastrointestinal; source: Lynch et al. (2017))
cough (activation, acute dosing; nervous system, respiratory, liver, cardiovascular, gastrointestinal; source: Lynch et al. (2017))
decreased gastric emptying (inhibition, acute dosing; nervous system, respiratory, liver, cardiovascular, gastrointestinal; source: Lynch et al. (2017))
decreased intestinal transit (inhibition, acute dosing; nervous system, respiratory, liver, cardiovascular, gastrointestinal; source: Lynch et al. (2017))
decreased pupil diameter (activation, acute dosing; nervous system, respiratory, liver, cardiovascular, gastrointestinal; source: Lynch et al. (2017))
decreased salivation (inhibition, acute dosing; nervous system, respiratory, liver, cardiovascular, gastrointestinal; source: Lynch et al. (2017))
diarrhea (activation, acute dosing; nervous system, respiratory, liver, cardiovascular, gastrointestinal; source: Lynch et al. (2017))
exhaustion (activation, acute dosing; nervous system, respiratory, liver, cardiovascular, gastrointestinal; source: Lynch et al. (2017))
frothing (activation, acute dosing; nervous system, respiratory, liver, cardiovascular, gastrointestinal; source: Lynch et al. (2017))
gastrointestinal smooth muscle constriction (activation; pulmonary, gastrointestinal; source: Bowes et al. (2012))
increased body temperature (activation, acute dosing; nervous system, respiratory, liver, cardiovascular, gastrointestinal; source: Lynch et al. (2017))
increased pupil diameter (inhibition, acute dosing; nervous system, respiratory, liver, cardiovascular, gastrointestinal; source: Lynch et al. (2017))
increased respiratory rate (activation, acute dosing; nervous system, respiratory, liver, cardiovascular, gastrointestinal; source: Lynch et al. (2017))
increased/decreased blood pressure (activation, acute dosing; nervous system, respiratory, liver, cardiovascular, gastrointestinal; source: Lynch et al. (2017))
increased/decreased heart rate (activation, acute dosing; nervous system, respiratory, liver, cardiovascular, gastrointestinal; source: Lynch et al. (2017))
irritability (activation, acute dosing; nervous system, respiratory, liver, cardiovascular, gastrointestinal; source: Lynch et al. (2017))
lacrimation (activation, acute dosing; nervous system, respiratory, liver, cardiovascular, gastrointestinal; source: Lynch et al. (2017))
liver failure (activation, acute dosing; nervous system, respiratory, liver, cardiovascular, gastrointestinal; source: Lynch et al. (2017))
muscle cramps (activation, acute dosing; nervous system, respiratory, liver, cardiovascular, gastrointestinal; source: Lynch et al. (2017))
neutrophil collection within the sinusoids (activation, acute dosing; nervous system, respiratory, liver, cardiovascular, gastrointestinal; source: Lynch et al. (2017))
pleural effusions (activation, acute dosing; nervous system, respiratory, liver, cardiovascular, gastrointestinal; source: Lynch et al. (2017))
and 4 more effects
Gene: Protein-coding gene on chromosome 1 (239,386,513 to 239,915,452, forward strand). Ensembl gene ENSG00000133019.
Subcellular location: Cell membrane; Postsynaptic cell membrane; Basolateral cell membrane; Endoplasmic reticulum membrane
Subcellular location (Human Protein Atlas): Plasma membrane; Nucleoli; Primary cilium tip; Vesicles
Pathways (Reactome):
Signal Transduction: G alpha (q) signalling events; Muscarinic acetylcholine receptors
Metabolism: Acetylcholine regulates insulin secretion
Gene Ontology:
Molecular function: protein binding; acetylcholine binding; G protein-coupled acetylcholine receptor activity; phosphatidylinositol-4,5-bisphosphate phospholipase C activity; signaling receptor activity; G protein-coupled receptor activity
Biological process: acetylcholine receptor signaling pathway; calcium-mediated signaling; adenylate cyclase-inhibiting G protein-coupled acetylcholine receptor signaling pathway; chemical synaptic transmission; G protein-coupled acetylcholine receptor signaling pathway; G protein-coupled receptor signaling pathway; G protein-coupled receptor signaling pathway, coupled to cyclic nucleotide second messenger; nervous system development; protein modification process; regulation of smooth muscle contraction; signal transduction; phospholipase C-activating G protein-coupled acetylcholine receptor signaling pathway; positive regulation of smooth muscle contraction; saliva secretion
Cellular component: basal plasma membrane; basolateral plasma membrane; endoplasmic reticulum membrane; plasma membrane; dendrite; synapse; membrane; postsynaptic membrane
Genetic constraint (gnomAD): Loss-of-function variants: 11 observed, 43.38 expected, observed/expected ratio (o/e) 0.25, 90% interval 0.16 to 0.42. The upper end of that interval is the gene's LOEUF score, 0.42, which puts it in group 1 of 6, group 1 being the genes least tolerant of losing a copy. Missense variants: 571 observed, 775.12 expected, observed/expected ratio (o/e) 0.74, 90% interval 0.69 to 0.79. Synonymous variants: 297 observed, 313.67 expected, observed/expected ratio (o/e) 0.95, 90% interval 0.86 to 1.04.
Homologues: Orthologues: chimpanzee CHRM3 (99% identical), macaque CHRM3 (98% identical), pig CHRM3 (96% identical), rabbit CHRM3 (95% identical), guinea pig CHRM3 (93% identical), dog CHRM3 (93% identical), mouse Chrm3 (92% identical), rat Chrm3 (92% identical), tropical clawed frog chrm3 (63% identical), zebrafish chrm3a (59% identical), zebrafish chrm3b (51% identical). Paralogues in human: CHRM5 (46% identical), CHRM1 (44% identical), CHRM2 (37% identical), CHRM4 (37% identical), HRH1 (20% identical), DRD5 (18% identical), HRH3 (18% identical), HTR1A (18% identical), HTR4 (17% identical), DRD1 (17% identical), DRD4 (17% identical), HTR1D (16% identical), and 13 more.
Diseases named in the same sentence as CHRM3 in open-access papers:
CHRM3 is named in the same sentence as 102 diseases in open-access papers, as found by Europe PMC text mining. Sharing a sentence is not in itself a finding about the gene and the disease. The quoted sentences say what the papers report.
colon cancer (18 papers, 2011 to 2025). "Another functional illustration revealed that TMEM147 adversely controlled calcium mobilization caused by the cholinergic receptor muscarinic 3 (CHRM3) and interfered with its trafficking to the cell membrane in colon cancer." (PMID 37305689, 2023). "Based on relatively small datasets, CHRM3, the gene encoding M3R, was reported to be overexpressed in 60–80% of colon cancers." (PMID 37835460, 2023). "For example, high CHRM3 levels are linked to invasion and metastasis in colon cancers; loss of EPN1 was linked to elevated VEGFR2 degradation and disorganized angiogenesis; and elevated PTGER3 levels was linked to shorter survival times in cervical cancers." (PMID 35991579, 2022). "CHRM3/M3R overexpression in colon cancer is associated with increased cell proliferation, metastasis, and a worse outcome, but little is known about the role of the other four muscarinic receptor subtypes." (PMID 35370785, 2022). "Of these three receptor subtypes, M3R are expressed widely in the gut and CHRM3, the gene encoding M3R, is reported to be uniquely over-expressed in colon cancer." (PMID 28416748, 2017). "Notably, in mice with combined Chrm1/M1R and Chrm3/M3R deficiency, M1R deficiency outweighs the effects of M3R deficiency; that is mice with combined M1R and M3R deficiency have as many colon tumors as control mice." (PMID 35370785, 2022). "We initially sought to verify that CHRM3, the gene encoding M3R, was over-expressed in colon cancer and to explore whether this was associated with any important clinical characteristics." (PMID 28416748, 2017). "Studies in colon cancer revealed that CHRM3 was able to facilitate ACh-induced EGFR signaling activation." (PMID 41516199, 2025). "In contrast, we found that CHRM1 mRNA expression is significantly reduced in human colon neoplasia and Chrm1 ablation in mouse models negates the anti-neoplastic effects of Chrm3 ablation; that is, Chrm1/M1R expression appears to protect against colon cancer." (PMID 37835460, 2023). "Cheng et al12 has revealed that BAs stimulate proliferation of H508 colon cancer cells which co-express both CHRM3 and EGFR." (PMID 36919835, 2023). "CHRM3 and M3 muscarinic receptors are commonly over-expressed in colon cancer and genetic ablation of Chrm3 or pharmacological inhibition of M3R activation in murine models of colon cancer attenuates tumor formation." (PMID 37835460, 2023). "The observed differential expression levels of this miRNA in both cell lines confirm that it acts as a tumor suppressor miRNA in all types of colon cancer cells and acts independent from CHRM3 gene." (PMID 36919835, 2023). "The expression of muscarinic receptors, mainly the M3 subtype (CHRM3), is amplified in several types of tumors, including colon cancer, prostate cancer, endometrial carcinoma, and gastric cancer." (PMID 37744266, 2023). "Collectively, these findings support the finding of increased CHRM3 expression but reduced CHRM1 expression in colon cancer." (PMID 37835460, 2023). "Targeting muscarinic receptors for illness therapy was established in several studies; for instance, CHRM3 antagonists (darifenacin and tiotropium) decreased lung and colon cancer proliferation." (PMID 37142586, 2023). "Colon cancer overexpresses CHRM3, and post-M3R signaling promotes cell growth via the activation of the epidermal growth factor receptors/ERK and protein kinase C/p38 mitogen-activated protein kinase (MAPK) signaling pathways." (PMID 37744266, 2023). "This study aims to investigate the possible role of CHRM3-targeted miRNAs using 2 human colon cancer cell lines: H508 strong-expressing CHMR3 and SNU-C4 weak-expressing CHRM3." (PMID 36919835, 2023). "Compared to adjacent normal colon, CHRM3 was over-expressed in 10 of 18 colon cancers (56%), a value consistent with those reported by others." (PMID 28416748, 2017).
colon cancer (continued). "Another limitation is that ours was a retrospective analysis; thus, although increased CHRM3 expression in the primary colon cancer appears to make it more likely metastases are present, we have not studied this prospectively." (PMID 28416748, 2017). "Several studies suggest important biological difference between cancers of the left and right colon; we examined the relationship between CHRM3 expression and the anatomic location, stage, and differentiation of colon cancer." (PMID 28416748, 2017). "This begs a question we cannot answer with certainty – Why does measuring CHRM3 mRNA expression underestimate M3R over-expression in colon cancer?" (PMID 28416748, 2017). "Confidence in this conclusion was bolstered by detecting over-expression of both mRNA and protein for ZNF277, the human analogue of Zfp277, in human colon cancer samples and, importantly, that this over-expression mirrored that of CHRM3 and M3R." (PMID 24694019, 2014). "When colon tumors were stratified by volume, a shift in tumor size in Chrm3-/- mice towards smaller lesions (< 2 mm3) became evident." (PMID 24694019, 2014). "In these 12 human tissue samples, over-expression of ZNF277 in colon cancer was contingent upon over-expression of CHRM3 (Spearman rank correlation coefficient = 0.73)." (PMID 24694019, 2014). "That is, concomitant genetic ablation of Chrm1 in Chrm3-/- mice appeared to mitigate reductions in both colon tumor number and volume that we repeatedly observed in AOM-treated Chrm3-/- compared to WT mice." (PMID 24694019, 2014). "CHRM3 are expressed widely in the GI tract and in colon cancer cells; in one small study, compared to adjacent normal tissue, in 63% of colon cancer specimens CHRM3 expression was increased up to 8-fold." (PMID 24212649, 2011). "When compared to AOM-treated WT mice, AOM-treated Chrm3−/− mice revealed 40% reduction in colon tumor number and 60% reduction in tumor volume." (PMID 24212649, 2011). "In normal colonic epithelium both CHRM1 and CHRM3 are expressed, while in colon cancer upregulation of CHRM3 expression is suggested." (PMID 24212649, 2011). "Increasing evidence in recent years has shown that CHRM3 may play a vital role in the carcinogenesis of many types of cancer, including colon cancer, lung cancer, and cholangiocarcinoma." (PMID 41516199, 2025). "The expression of CHRM3-dependent hsa-miR-1246 and hsa-miR-522-3p could play a critical role in tumor development via bile acid-related genes in colon cancer." (PMID 36919835, 2023). "This concept was again supported in the present work by our interrogation of a large public colon cancer database which confirmed that while CHRM3 levels were significantly elevated in cancer compared to those in normal colon tissue, CHRM1 levels were modestly, but significantly, reduced in cancer." (PMID 37835460, 2023). "In summary, we have demonstrated a novel anti-proliferative effect of M1R activation in human colon cancer cells that may explain why CHRM1/M1R levels in colon cancer are relatively reduced compared to CHRM3/M3R levels." (PMID 37835460, 2023). "However, little was reported regarding CHRM1 expression in colon cancer or relative CHRM1 versus CHRM3 expression." (PMID 37835460, 2023). "This analysis confirmed increased CHRM3 mRNA levels in colon cancer compared to adjacent normal colon; median CHRM3 transcript levels were elevated in 286 adenocarcinomas compared to 41 normal colon samples [2.528 vs. 1.272 transcripts per million, respectively (p = 0.002)]." (PMID 37835460, 2023). "Colon cancers might exhibit different patterns of genetic expressions and other colon cancer cell lines could be investigated for specific miRNA and CHRM3 expression as well." (PMID 36919835, 2023). "Moreover, CHRM1 transcript levels in colon cancer were significantly lower than CHRM3 transcript levels (p < 0.0005)." (PMID 37835460, 2023).